CCND1 (cyclin D1)
Diseases named in the same sentence as CCND1 in open-access papers (continued):
Sharing a sentence is not in itself a finding about the gene and the disease.
cervical carcinoma (continued). "All of the cervical cancer cells subjected to the MK treatment grew much more slowly and expressed less Akt1/p-Akt1, more p21/p27, less p-Rb and fewer molecules (p-GSK3β, β-catenin, c-myc and cyclin D1) of the Wnt/β-catenin signaling pathway than the cells that were not subjected to MK treatment." (PMID 27036045, 2016). "In conclusion, our study identified that miR-202 plays an important role in regulating cell proliferation, migration and invasion of CC by directly targeting cyclin D1, thus miR-202 may represent a potential therapeutic target for patients with cervical cancer." (PMID 27732565, 2016). "Sox2 could enhance the proliferation of cervical cancer cells by upregulating cyclin D1 expression." (PMID 26832364, 2016). "Our meta-analysis indicated that CCND1 G870A might be not the crucial risk factor for the development of cervical cancer." (PMID 25204741, 2014). "In conclusion, this meta-analysis indicated that CCND1 G870A polymorphism may not be a risk factor of cervical cancer development." (PMID 25204741, 2014). "However, some other studies did not reveal any significant associations between CCND1 G870A polymorphism and cervical cancer." (PMID 25204741, 2014). "This study further reveals that RBBP4 can regulate cisplatin sensitivity by modulating cyclin D1 expression, consistent with previous findings that RBBP4 knockdown inhibits epithelial-mesenchymal transition in cervical cancer cells." (PMID 40187236, 2025). "Cynaroside and Astragalin exert their cervical cancer inhibitory functions by regulating several signaling proteins (e.g., EGFR, STAT3, CCND1, IGFIR, ESR1)." (PMID 38003540, 2023). "The incubation of HeLa cervical cancer cells with PGG markedly decreased their viability, reduced the concentration of cyclin D1 and Bcl-2, and inhibited STAT3 phosphorylation." (PMID 37375411, 2023). "Notch1 induced cyclin D1 and CDK2 activity, two key molecules of cell proliferation in cervical cancer cells." (PMID 35740666, 2022). "MYC for cervical cancer, IDH1 for hepatic cirrhosis, MGMT for glioblastoma and CCND1 for anaplastic thyroid cancer were identified as genes with prognostic importance using survival analysis." (PMID 35001007, 2022). "We found inhibitory effects of CAR on cyclin D1 and CDK4 in cervical cancer cells suggesting its interference with cell cycle regulatory proteins." (PMID 36712982, 2022). "In cervical cancer, circ-E2F3 inhibits miR-296-5p increasing STAT3 nuclear translocation and upregulates expression of cyclin D1." (PMID 35444695, 2022). "The mRNA expression levels of CCND1, CCNE1, CDK2, CDK6, and p21CIP1 were significantly related to the histological classification of cervical cancer (p < 0.05)." (PMID 35246013, 2022). "It was found that the expression of proteins OVCA1, cyclin D1, and p16 increased in CIN and cervical cancer." (PMID 34830452, 2021). "All of these results indicated that PRDM4 inhibited cell proliferation and tumor growth, possibly by regulating cell cycle-related genes, including p27, p21, Cyclin D1, and CDK4, in cervical cancer." (PMID 33846573, 2021). "Our results demonstrated that quercetin combined with cisplatin has a synergistic effect on cervical cancer, leading to decreased protein expression of EGFR, MYC, CCND1, and ERBB2." (PMID 35070983, 2021). "Quercetin exerted a synergistic effect on cisplatin-treated cervical cancer cells primarily through downregulating the protein levels of EGFR, MYC, CCND1, and ERBB2 and upregulating CASP8." (PMID 35070983, 2021). "We also found that KD of WAPL in human cervical cancer cells reduced estrogen sensitivity and expression of ESR1 downstream genes, MYC and Cyclin D1." (PMID 33947962, 2021).
cervical carcinoma (continued). "In addition, a study demonstrated that the interaction of the E6 oncoprotein could also cause a decrease in the expression of a tsmiR, by which HPV16 E6 is able to decrease the level of miR-2861 expression, resulting in the suppression of the EGFR/AKT2/CCND1 pathway in cervical cancer cells." (PMID 33803022, 2021). "Polydatin efficiently inhibited cervical cancer cell proliferation by regulating cell cycle-related proteins including p21, p27, CDK2, CDK4, Cyclin D1, and Cyclin E1." (PMID 33912552, 2021). "In this study, MA has been shown as a potential candidate against cervical cancer by suppressing the expression level of MMP-7, β-catenin, c-Myc, and cyclin D1 in Wnt signaling cascade." (PMID 34421589, 2021). "In cervical cancer, a research group demonstrated that miR-2861 suppressed tumor cell growth and invasion by targeting EGFR/AKT2/CCND1 pathway." (PMID 32003757, 2020). "A promising new drug currently entering a peer-reviewed clinical trial for cervical cancer is sulfur heteroarotinoid A2 (SHetA2, NSC 726189), a small molecule flexible heteroarotinoid (Flex-Het) which targets cyclin D1 for degradation." (PMID 32429557, 2020). "In cervical cancer, these HPV-driven molecular events justify targeting the down-stream cyclin D1/CDK 4/6 complexes in development of much-needed, new molecularly targeted agents." (PMID 32429557, 2020). "STAT5B depletion also reduced cyclin D1 expression and increased p21 expression, confirming a role for STAT5 in HPV+ cervical cancer cell proliferation." (PMID 31817106, 2019). "Consistent with the mRNA results, a significant decrease of β-catenin, cyclin D1, and c-Myc protein expression was found in the SOX17 overexpressing cervical cancer cells." (PMID 29970906, 2018). "However, a few meta-analyses reported that the CCND1 G870A polymorphism may not be associated with an increased risk factor for cervical cancer and head and neck cancer." (PMID 29049220, 2017). "The effects of knockdown of ClC-3 expression by ClC-3 siRNA on cell cycle progression and expression of cyclin D1, CDK4, CDK6, p21 and p27 were also tested in the HeLa cell, a cell line derived from cervical cancer cells." (PMID 27451945, 2016). "To elucidate the regulatory mechanisms of miR-2861 in cervical cancer, we identified, for the first time, EGFR, AKT2, and CCND1 as the targets of miR-2861 in both SiHa and CaSki cells." (PMID 27364926, 2016). "The observed inhibitory effects of Cucurbitacin D on cyclin D1, CDK4 and phosphorylation of RB proteins in cervical cancer cells suggests its interference in cell cycle regulatory proteins." (PMID 27824155, 2016). "The USP25/KIFC1/MYCBP signal axis detected by RT-PCR did not change the expression level of c-MYC mRNA, but affected the expression levels of c-MYC transcription targets CDK4, CDK2, cyclin D1 and cyclin E which these have been reported to be regulated by c-MYC transcription in cervical cancer." (PMID 40379626, 2025). "Another investigation showed that FA (4 μM) could suppress migration of Hela and CaSki cervical carcinoma cell lines by increasing the cell cycle arrest in the G0/G1 phase and decreasing MMP9, mRNA expression, and cyclin D1 and cyclin E levels." (PMID 40487371, 2025). "As the results showed, PDK1 and β‐catenin were markedly more strongly expressed in cervical cancer tissue than in matched normal cervical tissue, and the downstream genes of the WNT pathway (cyclin D1, Snail) were consistently expressed according to the Western blotting analysis." (PMID 38733179, 2024). "Notably, our novel identification of CCND1 and CTCF as SMGs put the converging role of cell cycle progression in HPVU cervical cancer into clear perspective." (PMID 34572780, 2021).
cervical carcinoma (continued). "In conclusion, miR-29a-3p suppressed the migration and proliferation of cervical cancer cells by directly targeting SNIP1, and could also down-regulate the mRNA expression of SNIP1 downstream genes such as c-Myc, Cyclin D1 and HSP27." (PMID 33150075, 2020). "It is possible to speculate that cyclin D1 downregulation contributes to the survival of HPV(+) HNSCC tumor cells, similarly to cervical cancer." (PMID 32224897, 2020). "We proceeded to investigate whether the altered regulation of CCND1 and ODC1 proteins by eIF4E was present in the cervical cancer cells." (PMID 32981220, 2020). "Furthermore, consistent with the fact that p21 is a cyclin-dependent kinase inhibitor, we found that levels of cyclin-related proteins such as Cyclin D1, Cyclin E1, CDK2 and CDK4 were reduced in cervical cancer cells overexpressed by ST3Gal IV." (PMID 33598419, 2020). "Our results displayed that enhanced expression of DANCR upregulated the mRNA and protein expression levels of C-myc and Cyclin D1, and while knockdown of DANCR downregulated the mRNA and protein expression levels of C-myc and Cyclin D1 in cervical cancer cells." (PMID 32123519, 2020). "Furthermore, we identified a new pathway employing miR-2861, EGFR, AKT2, and CCND1 that mediates HPV16 E6 induced initiation and progression of cervical cancer." (PMID 27364926, 2016). "Given the functional roles of Cyclin D1 and ORAOV1 in cervical cancer tumorigenesis, the close proximity of these two genes on chromosome 11q13, it is interesting to determine whether there are interactions exist between these two genes." (PMID 20105337, 2010). "By upregulating miR-193b-3 expression and downregulating CCND1 expression, NEAT1 silencing can reduce the cell survival rate and clone formation, and increase G0/G1 phase cell cycle arrest and apoptosis, thus improving the radiosensitivity of cervical cancer cells." (PMID 35692795, 2022). "Baicalein inhibits cyclin D1 overexpression and arrests the cell cycle at G0/G1 phase through Wnt/β-catenin and protein kinase B/glycogen synthase kinase-3β (AKT/GSK-3β) signaling pathways to suppress proliferation and induce apoptosis of human cervical cancer HeLa and SiHa cells." (PMID 34680171, 2021). "We hypothesized that cyclin D1 degradation by the SHetA2 drug in combination with palbociclib inhibition of CDK4/6 activity synergistically reduces phosphorylated Rb (phospho-Rb) and inhibits cervical cancer growth." (PMID 32429557, 2020). "Furthermore, we report that TMS-TMF-4f could inhibit the induction of proliferative mediators such as Mcl-1, cyclin D1, survivin, and c-Myc via STAT3 inactivation, subsequently inducing apoptotic cell death in human cervical cancer cells." (PMID 31816985, 2019). "Furthermore, we confirmed that miR‐143‐5p inhibited the progression of the cervical cell cycle, proliferation, migration, and invasion, and inhibited cervical cancer cell apoptosis through downregulation of the protein expression levels of ELK1, p‐ELK1, C‐fos, Cyclin D1, and Bcl‐2." (PMID 28544557, 2017). "Thus, we identified a new pathway employing miR-2861, EGFR, AKT2, and CCND1 that may mediate HPV16 E6 induced initiation and progression of cervical cancer." (PMID 27364926, 2016).
glioblastoma (135 papers, 2006 to 2026). The most malignant astrocytic tumor (WHO grade IV). "Apoptosis in glioblastoma has been reported to be closely associated with the abundance of β-catenin, cyclin D1 (a known β-catenin-regulated gene), and Bcl-2." (PMID 37175205, 2023). "A systematic immunohistochemical (IHC) study to evaluate the association between cyclin D1 and survival of Glioblastoma patients, as well as the patterns of glioblastoma as defined in the new WHO Classification (2007), has yet not been performed." (PMID 35223330, 2022). "There was a significant increase in expression of p21, and this was tightly linked to the reduction in CDK4 and CCND1 in all glioblastoma cells after CKD5 treatment." (PMID 27852054, 2017). "Genetic aberration and over expression of cyclin D1 gene have been associated with higher degree of malignancy and increased rate of cell proliferation in several human neoplasms and glioblastomas." (PMID 24205314, 2013). "Cyclin D1 is a cell-cycle regulator essential for G1, phase progression and a candidate proto-oncogene implicated in pathogenesis of several human tumour types, including glioblastomas." (PMID 38225605, 2024). "In addition, DGKζ inhibition in U251 and U87 glioblastoma cells caused a marked decrease in cyclin D1 (CCND1) protein expression, which led to an arrest of cells at the G0/G1 phase." (PMID 32722576, 2020). "The G1 cell-cycle arrest induced by VA in 2D glioblastoma cells was coincident with decreased mRNA and protein levels of cyclin D1, the key regulator of G1 in S phase progression, and increased expression of CDK inhibitor p21 mRNA and protein." (PMID 40724848, 2025). "Isorhapontigenin exerts cancer-inhibitory effects on the growth of patient-derived glioblastoma spheres by inhibiting Cyclin D1 expression by regulating the miR-145/SOX2 axis." (PMID 40224178, 2025). "Reg-2 overexpression stalls glioblastoma cells in the G1 phase, and among its newly identified targets we have detected mRNAs for cyclin D1, and cyclins E1 and E2 that act in the early and late G1/S phase respectively." (PMID 38238463, 2024). "50% of glioblastoma patients have been found to harbour alterations in cyclin D1/CDK4/6-CDKN2A(p16INK4A)-Rb axis; hence, the use of CDK inhibitors in the treatment of glioblastoma warrants further investigation." (PMID 38212807, 2024). "Knockdown of CCND1 inhibited glioblastoma cell proliferation and invasion by simultaneously targeting multidrug resistance protein 1 (MDR1), B-cell lymphoma-2 (Bcl-2), and caspase-3." (PMID 39273281, 2024). "The findings from qRT-PCR-based investigations indicate the competency of garcinol in decreasing the gene expression of cyclin D1 in glioblastoma cells." (PMID 38435669, 2024). "Naringin treatment of U251 glioblastoma cells and U87 glioblastoma cells restricts their growth by inhibiting the cyclin D1 pathway or FAK pathway and induces the death of cells by inhibiting the BAD pathway or FAK pathway." (PMID 37570594, 2023). "Further research revealed that 5-Demethylnobiletin induces cell cycle arrest at the G0/G1 phase in glioblastoma cells by downregulating Cyclin D1 and CDK6 expression levels." (PMID 37139163, 2023). "A recent study reported that lncRNA RUNX1-IT1 can also sponge miR-195 to upregulate cyclin D1 in glioblastoma, thereby promoting cell proliferation." (PMID 35287551, 2022). "Induction of S-G2/M cell cycle arrest by RES has also been showed in human glioblastoma cell lines, and this has been accomplished by increasing levels of pCdc2 (Y15); cyclin A, B, and E; and by reducing cyclin D1." (PMID 35328780, 2022). "Western blot results showed that the growth-related proteins (CCND1 and β-catenin) of glioblastoma cells decreased following TRAF4 knockdown, consistent with previous studies." (PMID 36077559, 2022).
glioblastoma (continued). "Radu and colleagues have reported that the downregulation of Cyclin D1 induced by PTEN promotes cell G1 cycle arrest in glioblastomas." (PMID 36113340, 2022). "In this study, we will try to find out the exact relation between the expression of cyclin D1 and the survival of Glioblastoma patients." (PMID 35223330, 2022). "In conclusion, the KD enhanced the anti-tumor efficacy of Bev in a glioblastoma intracranial implantation mouse model, based on lowest levels of cellular proliferation markers (Ki67 and CCND1) in Beb + KD-tumors compared to the other groups." (PMID 33420169, 2021). "The analysis by Western blot showed that quinoin reduced the expression levels of Cyclin D1 in patient-derived glioblastoma cells NULU and ZAR, assuming that according to other mechanisms of RIPs action, quinoin induced a cell cycle arrest in G1/S phase." (PMID 34678977, 2021). "As there were a series of downstream molecules of this pathway involved in proliferation, apoptosis, migration, and invasion of glioblastoma, we examined some of the downstream molecules, including: Cyclin D1, p21, Bcl-2, Bax, MMP-2, and MMP-9." (PMID 32596388, 2020). "In glioblastoma, the research suggested that miR-708 affects glioblastoma cell proliferation, invasion, and apoptosis through regulating AKt1, CCND1, MMP2, EZH2, Parp-1 and Bcl219." (PMID 33028966, 2020). "While in our research, we found that HMGN5-siRNA arrested the cell cycle at the G1/G0 phase along with the decreased expression of Cyclin D1 and p21 protein in glioblastoma cells." (PMID 32596388, 2020). "Together, these data indicate that G. lucidum extract induced glioblastoma cells to arrest at S phase by inhibiting the expression of cyclin A2, cyclin D1, and CDK2." (PMID 32781747, 2020). "Suppression on STAT3 phosphorylation and EGFR/Akt/cyclin D1 signaling was reported to jointly contribute to cell cycle arrest in glioblastoma cells." (PMID 32877289, 2020). "SOX2 inhibition results in the downregulation of cyclin D1 and suppression of anchorage-independent growth and sphere formation of patient-derived glioblastoma." (PMID 30871066, 2019). "For example, downregulation of STIM1 expression inhibited glioblastoma U251 cell proliferation by inducing cell cycle arrest in the G0/G1 phase through regulation of p21Waf /Cip, cyclin D1 and CDK4." (PMID 31564210, 2019). "In this study the high expression of cyclin D1 was observed in high-grade astrocytic tumors, particularly Glioblastoma multiforme." (PMID 31583003, 2019). "Although it has been reported that elevated cyclin D1 expression in human glioblastoma correlates with a poor prognosis, one study demonstrated that higher cyclin D1 levels were present in the glioblastoma group." (PMID 31583003, 2019). "LP resveratrol-treated glioblastomas showed less Cyclin D1 staining, enhanced autophagy with up-regulated LC3 and Beclin1 expression, and widely distributed apoptotic foci around tumor capillaries with suppressed STAT3 expression and nuclear translocation." (PMID 27716625, 2016). "What’s more, researchers have discovered that overexpression of CCND1 can elevate the proliferation and invasion potential of human glioblastoma cells." (PMID 27716259, 2016). "The role of cyclin D1 degradation in human glioblastoma cell differentiation was then experimentally verified." (PMID 27515956, 2016). "In contrast, the overexpression of CCND1 increased the proliferation and invasive capacity of both human glioblastoma cell lines but reduced apoptosis." (PMID 26317630, 2015). "Common alterations in the cyclin D1-cyclin-dependent kinase 4/6-retinoblastoma 1 pathway in glioblastoma make PD0332991 also an interesting drug for the treatment of glioblastoma." (PMID 26649278, 2015). "In glioblastoma cell lines, it has been reported that cyclin D1 overexpression promotes invasiveness in vitro." (PMID 24438171, 2014).